INS (insulin)
Diseases named in the same sentence as INS in open-access papers (continued):
Sharing a sentence is not in itself a finding about the gene and the disease.
Hyperglycemia (continued). "As a result of this cell aberration, insulin release is reduced, resulting in hyperglycaemia and prolonged hyperglycemias was considered to be the pre condition for the advancement of diabetic complications." (PMID 36404830, 2022). "Despite the initial near-normoglycemia remission, most DKA/SH individuals develop hyperglycemia relapse after insulin discontinuation." (PMID 35721763, 2022). "T2DM is a metabolic disease characterized by hyperglycemia and insufficient secretion or action of endogenous insulin." (PMID 35630566, 2022). "Vascular endothelium is the primary target of hyperlipidemia, hyperglycemia, and insulin in metabolic disorders and diabetes, leading to endothelial dysfunction and cardiovascular complications at various stages of pathological changes." (PMID 36551937, 2022). "The OGTT and ITT showed that SZ-A alleviated hyperglycemia after oral glucose load and IP injection of insulin in a dose-dependent manner." (PMID 35308210, 2022). "It has been proven in perioperative studies, coronary care, and prospective randomized trials that aggressive treatment of hyperglycemia with insulin lowers morbidity and death." (PMID 36557312, 2022). "GIP infusion was found to induce lipolysis, shown as increased plasma NEFA and glycerol concentrations, during stable basal insulin substitution and hyperglycemia in men with type 1 diabetes." (PMID 36010335, 2022). "Cow’s milk whey protein isolate (WPI) is an insulin secretagogue which can suppress hyperglycemia in prediabetes." (PMID 36992769, 2022). "The feeding of high starch led to the production of hyperglycaemia in largemouth bass, which in turn induced an increase in insulin secretion by pancreatic β-cells." (PMID 35677086, 2022). "Insulin is very effective and can be considered in the presence of severe hyperglycemia, particularly if complications are detected such as hypertriglyceridemia, weight loss, and ketosis." (PMID 35233335, 2022). "Administration of VDAC1 inhibitor improved insulin secretion, glucose intolerance and hyperglycemia in obese diabetic mice." (PMID 35800345, 2022). "GLP-1 can stimulate glucose-dependent insulin secretion, thereby reducing postprandial hyperglycemia." (PMID 35784557, 2022). "Stress hyperglycemia has long been regarded as an adaptive and beneficial stress response, ensuring adequate cellular glucose uptake in non-insulin-dependent, obligatory glucose-consuming tissues such as the brain, phagocytes and reparative cells." (PMID 35578303, 2022). "In mammals, chronic hyperglycemia is mainly due to an alteration in insulin production, secretion and signaling." (PMID 35628176, 2022). "In our study, exogenous insulin therapy was introduced to control hyperglycemia and ensure the survival of severely diabetic NOD mice with BG >30 mmol/L, similar to the necessity of insulin therapy in human patients with T1D." (PMID 36339443, 2022). "During pregnancies complicated by maternal obesity or GDM, both maternal and fetal insulin levels are high in response to maternal hyperglycaemia." (PMID 35258482, 2022). "In the overall population, among potentially associated clinical complications, nosocomial infections (31.1%) and insulin use for hyperglycaemia (26.5%) were the most frequently observed, occurring with similar rate in the two groups." (PMID 35482703, 2022). "T1D patients depend on exogenous insulin throughout life, and their wellbeing is typically compromised by both hyperglycaemia (a consequence of poor control of the disease) and hypoglycaemia, due to improper insulin treatment." (PMID 36455476, 2022). "Decreased insulin leads to abnormal glucose metabolism pathways, which further results in hyperglycemia." (PMID 36358477, 2022). "Diabetes has been described as a chronic metabolic disorder resulting from the inability of the body to either produce or use insulin for the control of postprandial hyperglycemia." (PMID 36161374, 2022).
Hyperglycemia (continued). "The insulin-producing β cells in the pancreas are destroyed by the autoimmune system, leading to hyperglycemia." (PMID 35903090, 2022). "In diabetic individuals and those suffering from metabolic syndrome, this interplay between insulin and other regulatory hormones is lost; β-cells are unable to produce sufficient insulin levels to keep up with the demand, resulting in overt hyperglycemia." (PMID 35883660, 2022). "Due to a compensation mechanism of the body attempting to produce more insulin, the body increases insulin production to combat hyperglycaemia, leading to an increase in the size of islet cells and pancreatic β-cells." (PMID 36671612, 2022). "Results from in vitro models supported a pro-inflammatory role for uric acid and its combination with insulin in monocytes and for uric acid alone in hyperglycaemia-stimulated endothelial cells." (PMID 35503137, 2022). "Some groups, reported to deliberately omit insulin doses to induce hyperglycemia to get exam exemptions or avoid family problems." (PMID 38515508, 2022). "Initial aggressive treatment with insulin therapy and antidiabetic drugs such as metformin predict better outcomes and a delay in the recurrence of hyperglycemia." (PMID 35743358, 2022). "Although ubiquitously expressed, transcription of SGK1 is highly regulated by various cellular events, such as hyperglycemia, ischemia, and cancer, and stimulated by glucocorticoids, mineralocorticoids, insulin, and TGFβ." (PMID 36457711, 2022). "DM is a state of impaired metabolism characterized by hyperglycemia, resulting from defects in insulin secretion or action, or both." (PMID 35164215, 2022). "Treatment of Zucker diabetic fatty rats with the antioxidant NAC prevented hyperglycemia, glucose intolerance, and defective insulin secretion." (PMID 36139075, 2022). "The management of hospitalized patients with hyperglycemia can be complicated by various circumstances, and they are usually treated with insulin." (PMID 35017617, 2022). "In parallel, periodontal bacteria alter glucose and lipid metabolism in the liver and deregulate insulin production by pancreatic β-cells, contributing to hyperglycemia." (PMID 35327570, 2022). "Hyperglycemia with high plasma insulin concentrations is the result of insulin insensitivity that occurs during the acute phase of stress." (PMID 35565787, 2022). "The major objective of insulin therapy during Ramadan is to provide adequate insulin to prevent the post meal (After Iftar) hyperglycemia and also prevent hypoglycaemia during the period of fast." (PMID 35308269, 2022). "Type 2 DM is a metabolic disorder characterized by prolonged periods of elevated blood glucose (hyperglycemia), which results in insulin resistance in peripheral tissues or impaired insulin production by pancreatic B cells." (PMID 36064352, 2022). "FGF21 can tackle several important aspects of DM, by increasing insulin sensitivity, reducing hyperglycemia, improving the lipid metabolism profile of the blood, and inducing weight loss." (PMID 36699319, 2022). "Nevertheless, patients with T2DM who are insulin resistant always present mainly hyperglycemia and rare hypoglycemia, consequently undergo a much smaller glucose variability than that of T1DM." (PMID 36204110, 2022). "The present study investigated the effect of thiamine disulfide (TD) on the pancreas in terms of hyperglycemia improvement and insulin sensitivity increase in diabetic male rats." (PMID 35725834, 2022). "Owing to the limitations and off-target side effects of antidiabetic drugs, exercise-induced control of hyperglycemia and increased insulin sensitivity is a preferred strategy to manage “diabesity” associated complications." (PMID 36531176, 2022). "Hyperglycemia produces glucose toxicity in tissues with an insulin-independent glucose absorption route." (PMID 35600869, 2022).
Hyperglycemia (continued). "The COVID-19 severity and death predictors include male gender, age, cardiovascular disease, chronic kidney disease, chronic obstructive pulmonary disease, insulin use, and hyperglycemia." (PMID 36498037, 2022). "In different cell types, such as adipocytes and ß-islet cells, statins are described to have a positive effect on insulin sensitivity and hyperglycemia." (PMID 35216514, 2022). "Pcsk1fl/flPdx-CreERT were implanted subcutaneously with insulin pellets which prevented hyperglycemia and hyperphagia." (PMID 35963866, 2022). "The main processes responsible for stress hyperglycemia are insulin resistance and increased gluconeogenesis." (PMID 35457586, 2022). "ZDF beta cells initially met the challenge of hyperglycemia by secreting increasing amounts of insulin." (PMID 36632484, 2022). "Simultaneously, the increased effort exerted by beta cells to counteract chronic hyperglycemia can lead to cellular exhaustion, thus damaging the population of beta cells and inhibiting future insulin release." (PMID 36532060, 2022). "In one hospital, daily reports are automatically generated for patients with hyperglycemia and hypoglycemia defined as 2 or more readings of ≥ 225 mg/dL and < 70 mg/dL, respectively, on insulin pumps, and those with type 1 diabetes, in the preceding 24 h." (PMID 35917098, 2022). "An insulin-resistant metabolism is hallmarked by hyperglycemia, elevated free fatty acids (FFA), and a chronic state of inflammation mediated through cytokines such as interleukin-1β (IL-1β), interferon-γ (IFN-γ), and tumor necrosis factor-α (TNF-α)." (PMID 35453472, 2022). "DM is a prolonged disturbance related to irreversible destruction of islet β-cells insulin production, which is determined by hyperglycemia and altered fat metabolism." (PMID 35711333, 2022). "This is attributed to low insulin level, high blood glucose (hyperglycemia), and autoimmunity-induced inflammation." (PMID 36578470, 2022). "The vasopressin receptor V1b is expressed both on α and β cells and can regulate glucose homeostasis in a glucose-dependent way, which increases insulin during hyperglycemia and increases glucagon during hypoglycemia." (PMID 35669692, 2022). "STZ is taken up by pancreatic β-cell via the glucose transporter, causing DNA fragmentation and cell death, as well as the generation of free radicals such as hydrogen peroxide, which leads to a decrease in insulin production and hyperglycemia." (PMID 35345832, 2022). "Our results confirm that most subjects show an anti‐phasic relationship between glucagon and insulin during hyperglycemia, as previously observed in pigs and in humans after a meal." (PMID 35822422, 2022). "Current guidelines recommend a basal-bolus regimen for treatment of GC-induced hyperglycemia, but we found similar outcomes with pre-mixed and bolus-only insulin regimens." (PMID 34986826, 2022). "Several previously published studies support our suggestion, showing that postprandial hyperglycemia is more effectively controlled, when prolonged methods of insulin administration are used instead of the SB." (PMID 35330014, 2022). "Nonetheless, hyperglycemia was increasing as the afternoon proceeded and rapid-acting insulin boluses were needed for afternoon snack and dinner." (PMID 35178031, 2022). "When receptor resistance exceeds the capacity of the pancreas to secrete enough insulin to compensate for this resistance, hyperglycemia occurs." (PMID 35884888, 2022). "Inflammation normally affects insulin and glucose metabolism via cytokines such as TNF-α and Interleukin 6, and predispose to hyperglycemia." (PMID 37092113, 2022). "Meals characterised by low GI values reduced post-prandial hyperglycaemia as well as insulin response among patients." (PMID 36011551, 2022). "Mice proffered the mSAD for 15 weeks displayed a phenotype consistent with metabolic syndrome, exhibiting increased adiposity, fasting hyperglycemia with impaired glucose and insulin tolerance." (PMID 36105576, 2022).
Hyperglycemia (continued). "Citrus flavonoids, such as hesperetin, have shown potential in attenuating hyperglycemia in streptozotocin (STZ)-induced diabetes in rats by releasing insulin from β cells of islets." (PMID 35204122, 2022). "On the other hand, the patients who eventually required insulin treatment were those that developed rapid hyperglycemia after the first injection of pasireotide LAR." (PMID 35090028, 2022). "A defective GNT glycosyltransferase in the pancreatic islets results in impaired insulin action, impaired glucose tolerance and eventually, hyperglycaemia." (PMID 35768493, 2022). "The pathogenesis of T2D involves abnormalities in both peripheral insulin action and insulin secretion by pancreatic β-cells, resulting in hyperglycemia." (PMID 35406040, 2022). "The standard approach to the management of hyperglycemia in infants involves the use of glucose restriction and/or continuous insulin infusion to achieve a normal level of glycaemia, while maintaining an adequate caloric intake." (PMID 35135591, 2022). "Specifically, standard diet-fed mice harboring OGT deletion in β cells exhibited severe hyperglycemia, glucose intolerance, impaired insulin secretion and developed severe diabetes due to β cell failure." (PMID 35527999, 2022). "Our study results show that insulin was the sole mediator in the relationship between increased BMIz and intermediate hyperglycemia." (PMID 35757631, 2022). "The dysregulated insulin signaling in GDM results in hyperglycemia that subsequently leads to increased inflammation, oxidative stress, and hyperlipidemia." (PMID 36249983, 2022). "At a later stage, the pancreatic β-cells cannot compensate for the high demand of insulin; therefore, this eventually leads to β-cell dysfunction and defect in insulin secretion, and hyperglycemia occurs." (PMID 36232291, 2022). "Injection of bone marrow MSCs into diabetic mice can increase insulin levels and downregulate hyperglycemia; the exosomes derived from human umbilical cord stem cells (hUCMSCs) can enhance insulin sensitivity." (PMID 35370989, 2022). "Goto-Kakizaki rats exhibited enzymatic impaired PRMT1 activity and defective protein methylation when stimulated by postprandial hyperglycemia, indicating the potential involvement of protein methylation in mediating insulin secretion." (PMID 35087408, 2021). "Randomised controlled trials are needed to clarify the role of insulin in treating hyperglycaemia in extremely preterm infants." (PMID 33863775, 2021). "Group two (1 unit of insulin) showed stable and higher average HbA1c values of around 7–8% over three months of consistent hyperglycaemia." (PMID 33557206, 2021). "Damage to pancreatic β cells leads to a decrease in insulin secretion, while liver damage leads to a decrease in the sensitivity of the liver to insulin, leading to hyperglycemia and insulin resistance." (PMID 34722505, 2021). "Given the logistic challenges in performing a formal mixed meal test in CIADM patients we recommend a post-prandial C-peptide as an alternative, assessing for inappropriately low insulin production in a setting of relative hyperglycaemia." (PMID 34803927, 2021). "Hormone imbalance is also observed after PD, with decreased insulin secretion leading to hyperglycemia and increased GLP-1 secretion, both of which are known to delay gastric emptying." (PMID 34200183, 2021). "Consistent with this, PGLP-1-VP treatment can significantly ameliorate hyperglycemia, reduce food intake and improve glucose and insulin tolerance as well as PGLP-1 in STZ-induced hyperglycemic mice model." (PMID 33574570, 2021). "The drug-loaded polymeric vesicles effectively released insulin in response to hyperglycemia insulin and glucose oxidase (GOx) encapsulation." (PMID 34372008, 2021). "Once there is dysregulation of these physiological functions, such as delayed or decreased insulin secretion, hyperglycemia occurs." (PMID 34400887, 2021).
Hyperglycemia (continued). "Typically, pancreatic β-cells counteract for the diminished effect of insulin through increasing the release of insulin to reverse hyperglycemia; however, as IR worsens, this compensatory mechanism becomes less effective." (PMID 35011414, 2021). "Hyperglycemia deteriorates pancreatic insulin secretory capacity and peripheral insulin sensitivity." (PMID 34371645, 2021). "In β-cells, decreased AKT activity and activation of FoxO1 is attributed to loss of mTORC2 that resulted into glucose intolerance and mild hyperglycemia as the mass of β cell get decreased consequently to decline in production and secretion of insulin." (PMID 34535145, 2021). "Unfortunately, even when insulin is administered as directed, hyperglycemia is very difficult to control." (PMID 33800470, 2021). "Both animal and human studies have shown that supplementation with cornelian cherries can be an effective means of reducing blood glucose levels in those with hyperglycemia, increasing insulin sensitivity and improving insulin resistance." (PMID 34401109, 2021). "The present results indicate that active smoking not only induced aberrations in the oral and gastrointestinal microbiomes, but it also led to hyperglycemia, reduced serum insulin and leptin levels." (PMID 34917518, 2021). "In our study, cholesterol metabolism and insulin tolerance are disturbed more rapidly than the occurrence of hyperglycemia and body overweight in response to HFD." (PMID 34327200, 2021). "Due to postprandial hyperglycemia he was treated with insulin glargine for several years in addition to a galactose-restricted diet." (PMID 34828390, 2021). "It is commonly accepted that hyperinsulinemia is consequent to resistance to insulin action in glucose metabolism, leading to increased glycaemia, which in turn stimulates the pancreatic β-cell to release insulin to avoid a more severe hyperglycemia." (PMID 33712379, 2021). "DM is a set of metabolic diseases characterized by hyperglycemia due to defects in the secretion of insulin, its action or both." (PMID 35096863, 2021). "In contrast to the current results, those of some studies have indicated that doxepin treatment can attenuate hyperglycemia and increase IS and insulin secretion in humans and animals." (PMID 33809508, 2021). "There is scarce information about the effects of stress-related hyperglycemia and its effect on insulin secretion and HOMA-IR." (PMID 33461546, 2021). "It has been shown that intraperitoneal insulin infusion allowed better control in unannounced meals, with a reduction of time spent in hyperglycemia in the postprandial phase." (PMID 33755854, 2021). "Other studies with rAAV-lep have found that a single icv injection can reverse hyperglycemia by increasing the rate of glucose disposal and improving insulin sensitivity in diabetic mice." (PMID 34947993, 2021). "Our study thus shows that protocols for insulin adjustment and CHO intake reduce the risk for hyperglycemia but are limited in their effectiveness to avoid hypoglycemia, especially in patients under MDI regimens." (PMID 34512541, 2021). "Hyperglycemia is postulated to result from an insulin supply inadequate to meet demands of normal blood glucose regulation due to β-cell dysfunction." (PMID 34884524, 2021). "IHPs include nursing diagnoses, student outcome goals, outcomes, indicators, interventions, and delegation, and emergency health plans include glucose monitoring, insulin dosage, snacks, exercise, and protocols for hypoglycemia and hyperglycemia." (PMID 33567721, 2021). "Emerging studies have demonstrated that, in addition to its role in body weight regulation, adipocyte-derived leptin is capable of reducing T1D hyperglycemia in an insulin-independent manner." (PMID 33976218, 2021). "Apart from directly promotes cancer progression, hyperglycemia increases the levels of insulin/IGF-1 and inflammatory cytokines in circulation." (PMID 34527591, 2021).